AREG (amphiregulin)
Diseases named in the same sentence as AREG in open-access papers (continued):
Sharing a sentence is not in itself a finding about the gene and the disease.
tumor (continued). "To determine the target cells of IL1RL1+ Treg–derived AREG in the TME, we looked in our whole tumor scRNA-seq data to see which cell types expressed Egfr, the only known receptor for AREG." (PMID 37611111, 2023). "Dying tumour cells create amphiregulin (AREG)‐ and basic fibroblast growth factor (bFGF)‐based extracellular environments via cytotoxic treatment‐induced endoplasmic reticulum stress." (PMID 36639835, 2023). "Further experimental results indicate that the ADAM17 shedding heparin-binding epidermal growth factor (HB-EGF) and amphiregulin in tumour cells are molecular mediators of macrophage education." (PMID 38069391, 2023). "Toll-like receptors also induce tumor proliferation mediated by mitogens such as hepatocyte growth factors, amphiregulin and epiregulin." (PMID 38138294, 2023). "Among the differentially expressed cytokines, we focused on AREG and bFGF to identify the cytokines responsible for stimulating tumour cell repopulation." (PMID 36639835, 2023). "Of course, the roles and mechanisms of AREG and bFGF in tumour cell repopulation and recurrence in cancer need further investigation." (PMID 36639835, 2023). "The EGFR/AREG axis activation, coupled with the mutational patterns in PI3K/AKT/mTOR and cell cycle pathways warrants caution in considering MECs as low‐risk neoplasms." (PMID 36916425, 2023). "Third, concerning the direct mediators from dying cells that promote tumour cell repopulation, the cytokines AREG and bFGF were identified in this study, suggesting the critical roles of the paracrine niche created by dead cells." (PMID 36639835, 2023). "Biologically, AREG‐ and bFGF‐neutralising Abs synergistically inhibited reporter tumour cell repopulation induced by feeder cells in vitro." (PMID 36639835, 2023). "The NF‐κB signal was markedly activated as a critical signalling pathway for tumour cell repopulation by conditioned culture medium or AREG and bFGF2 synergistically." (PMID 36639835, 2023). "We demonstrate that in cytotoxic therapy‐induced dying tumour cells, ROS/lipid peroxidation–ER stress signalling triggers AREG and bFGF secretion to establish a population‐promoting extracellular environment." (PMID 36639835, 2023). "Whole tumor single-cell RNA sequencing (scRNA-seq) analysis and blockade experiments revealed that the amphiregulin (AREG)–epidermal growth factor receptor (EGFR) axis mediated cross-talk between IL1RL1+ Treg cells and CAFs." (PMID 37611111, 2023). "Here, we found that AREG and bFGF2 from dying tumour cells synergistically promoted the proliferation of living tumour cells." (PMID 36639835, 2023). "This suggests that AREG has limited value as a tumor marker, so we restricted our subsequent studies to Nectin-4 and HB-EGF." (PMID 36497350, 2022). "The inhibition of amphiregulin promotes tumor regression and suppresses chemical resistance in vivo." (PMID 36612193, 2022). "Cytokine secretion, such as interleukin-4 (IL-4), IL-5, IL-9, IL-13, and amphiregulin (Areg), by type 2 innate lymphoid cells (ILC2s) is indispensable for homeostasis, remodeling/repairing tissue structure, inflammation, and tumor immunity." (PMID 35592688, 2022). "Taken together, these findings suggest a critical role of the ADAM17-EGFR (HB-EGF/AREG) axis in the polarization of TAMs, which also provides a new strategy for the anti-tumor immunotherapy." (PMID 36466812, 2022). "On analyzing the results, three proteins were found elevated: CXCL16, amphiregulin (a tumor progression protein), and tissue inhibitor metalloproteinases (TIMP1)." (PMID 36358879, 2022). "Amphiregulin produced from senescent stromal cells enhances PD-L1 expression in cancer cells and creates an immunosuppressive tumor microenvironment." (PMID 36612193, 2022). "Co-expression of Amphiregulin with EGFR, as seen on PANC1 cells, results in an autocrine feedback loop that associates with poor tumor differentiation." (PMID 35337112, 2022).
tumor (continued). "We analyzed all seven known EGFR ligands (soluble form) in the tumor tissues but detected only AREG and HB-EGF." (PMID 35650607, 2022). "On the other hand, amphiregulin‐stimulated ILC2s can establish an immunosuppressive tumour microenvironment." (PMID 35344301, 2022). "We also noted that the tumor enriched C5 cells were characterized by the expression of resting NK cells markers, such as AREG, XCL1, and KLRC1, while the C9 cells, which expressed the CX3CR1 and NKG7, were abundant in normal tissues." (PMID 36008393, 2022). "High Amphiregulin, PTEN, and low P21 expression levels were associated with a low grade of the tumor (p= 0.038 and 0.025 respectively) (p > 0.05)." (PMID 33906293, 2021). "In CCS, amphiregulin expression was directly proportional to tumor grade; it was expressed in 27.66% of tumors located in the long bones and 52.63% in the flat bones." (PMID 34468540, 2021). "Additional experiments observed similar results in NSG mice, which further established the role for tumor-derived (autocrine) AREG." (PMID 33941851, 2021). "In the present study, we detected significantly upregulated amphiregulin expression in patients with CCS that evolved with tumor metastasis." (PMID 34468540, 2021). "Reciprocally, tumor-associated macrophages highly express CXCR2, HB-EGF, AREG, and ADAM proteinases, but EGFR is only weakly expressed." (PMID 33941851, 2021). "Initially, when applying RNA-seq on tumor cells of different aggregation conditions, the authors found that epigen (along with amphiregulin) was the most induced gene upon tumor cell clustering." (PMID 34100888, 2021). "Under these conditions, the AhR−AREG (Amphiregulin) signaling pathway positively supports tumorigenesis by controlling ROS and shaping the pro-tumorigenic functions of the tumor microenvironment." (PMID 33451095, 2021). "These γδ T cells then produced IL-17 to promote neutrophil infiltration and inflammation in the tumor microenvironment; they also expressed IL-22, amphiregulin, and other effector molecules to directly enhance tumor cell proliferation." (PMID 34108973, 2021). "Consistent with AREG being a CSF-1R regulated gene, AREG also has pleiotropic roles during tumor development." (PMID 34843542, 2021). "Therefore, our finding that Amphiregulin regulates TGF-β function under inflammatory conditions may propose targeting Amphiregulin activity as an attractive alternative therapeutic approach in the context of tumor therapy or chronic inflammation-associated fibrotic diseases." (PMID 30770250, 2019). "While high level of IL13Rα2 expression inhibited cell proliferation in vitro, it also promoted the expression of amphiregulin, a proangiogenic factor, which in turn resulted in enhanced angiogenesis and increased tumour formation in vivo." (PMID 30718742, 2019). "Using RT-qPCR-based gene expression assays on RNA extracted from the 98 tumor samples, we found a statistically significant higher expression of both AREG and EREG in the basal tumors (ANOVA p < 0.001)." (PMID 31181806, 2019). "AREG, a member of the EGF family, was reported as having high expression in CRC and was associated with tumor invasion, liver metastasis, and lower survival." (PMID 31213644, 2019). "Knockdown of EGFR, AREG or TGFα expression resulted in decreased tumor cell motility, slower growing tumor cells, and increased survival." (PMID 31681327, 2019). "We observed ADAM9‐dependent shedding of HB‐EGF in both tumor cell lines as well as ADAM9‐dependent shedding of amphiregulin in MiaPaCa‐2 cells." (PMID 30556643, 2019). "Overexpression of AREG, TGFα or both ligands increased tumor burden, increased tumor vascularity, increased number of infiltrating macrophages, and portended poorer survival." (PMID 31681327, 2019). "In contrast to cetuximab, however, AREG mAb generated significantly, albeit slightly more apoptotic cells in tumor xenografts." (PMID 31493351, 2019).
tumor (continued). "Conversely, knockdown of AREG from PSC27AREG cells prior to tumor implantation resulted in considerably reduced tumor volumes (39.5% and 42.5% for shRNAAREG#1 and shRNAAREG#2, respectively, p < .0001 for both)." (PMID 31493351, 2019). "In mammary glands prior to tumor development, melatonin supplementation alone and combined with HT reduced amphiregulin expression and increased tertiary branching in MEL and MEPT mice." (PMID 31355130, 2019). "Patients and Methods: Formalin-fixed paraffin-embedded (FFPE) tumor samples from surgically removed primaries of the AIO KRK-0207 trial have been tested for AREG and EREG expression." (PMID 30467535, 2018). "To elucidate the ligand responsible for activation of EGFR, we examined the effects of the tumour‐promoting DCA on AREG, TGF‐α and HB‐EGF by ELISA assay in IMCE and HCT‐116 cell lines." (PMID 29956475, 2018). "EREG and AREG levels have been shown to predict tumor response and disease control in patients treated with EGFR-antibodies in both, RAS or KRAS exon 2 wild-type populations." (PMID 30467535, 2018). "To better understand the implications of histological differences on tumor growth, we assessed AREG+/+ and AREG−/− tumors for the presence of necrosis (H&E images)." (PMID 30367629, 2018). "Out of 371 tumor samples, 331 had measurable AREG and EREG expression levels (see CONSORT diagram for all subgroups)." (PMID 30467535, 2018). "We evaluated tumor growth, cytokeratin-8 (K8)-positive luminal cells, cytokeratin-14 (K14)-positive myoepithelial cells, and expression of AREG, Ki67, and PyMT." (PMID 30367629, 2018). "When we compared the percentage of each tumor occupied by solid or papillary histology, we found that AREG−/− tumors had a significantly greater proportion of papillary tumor histology than AREG+/+ tumors." (PMID 30367629, 2018). "As a result, AREG−/− tumors form a wider range of tumor morphologies, including less aggressive papillary and cystic structures." (PMID 30367629, 2018). "Targeting specifically the crosstalk between immune and epithelial cell via amphiregulin still holds promise for the development of therapeutics to combat non-neoplastic diseases and cancer." (PMID 29225597, 2017). "A growing number of studies support the concept that amphiregulin is indispensable for tissue integrity, and ultimately to abstain tumor development." (PMID 29225597, 2017). "Trop2 and AREG mRNA level were 2.12 ± 1.14, 1.80 ± 1.03 fold higher in GC tissues than in matched tumor neighbor tissues, respectively (P < 0.001)." (PMID 28256068, 2017). "Lastly, an analysis of patient tumor samples reveals an association between RNA expression levels of NRG1, and two EGFR ligands amphiregulin (AREG) and transforming growth factor α (TGFα)." (PMID 28723928, 2017). "For example, increased amphiregulin levels have been found in non-neoplastic diseases, including inflammatory diseases and autoimmune diseases." (PMID 29225597, 2017). "Monitoring of tumor growth showed that AREG markedly increased tumorigenicity, which was suppressed by miR-34c-5p significantly." (PMID 28459431, 2017). "In tumor cells treated with PGE2 for 60 min the levels of AREG and EREG increased, whereas in the presence of c-SRC inhibitors (PP1 or SU6656) or ADAM-MMPs inhibitor (GM6001), AREG and EREG levels declined towards the baseline." (PMID 28415726, 2017). "The qRT‐PCR was performed in 26 pairs of fresh GC tissues and matched tumor neighbor tissue to further investigated the correlation between Trop2 and AREG expression in GC." (PMID 28256068, 2017). "Among the family of HER receptor ligands, amphiregulin (AREG) and epiregulin in particular have been studied for their involvement in the responsiveness of tumours to cetuximab-containing regimens." (PMID 27933395, 2017). "In a cellular model, AREG acted as an autocrine growth factor and evoked the induction of growth signaling to promote tumor cell proliferation and tumor angiogenesis." (PMID 27713123, 2016).
tumor (continued). "The relationships between each protein expression level and the clinicopathologic factors were examined, only AREG/EGFR co-expression was significantly related to tumor differentiation (P = 0.032)." (PMID 27391842, 2016). "Univariate survival analysis proved that high tumor-node-metastasis (TNM) stage, poor tumor differentiation and AREG expression were significant poor prognostic factors for disease-free survival (DFS) and overall survival (OS)." (PMID 27391842, 2016). "A significant association between AREG/EGFR co-expression and tumor differentiation was observed in our study (P = 0.032)." (PMID 27391842, 2016). "AREG activates signalling in an autocrine manner in tumour cells, but it is also able to activate EGFR via paracrine signals from non‐resident cells of the microenvironment." (PMID 27196940, 2016). "In the univariate survival analysis, high TNM stage (P = 0.003 and P = 0.001), poor tumor differentiation (P = 0.009 and P = 0.002) and AREG expression (P = 0.021 and P = 0.003) were significant adverse prognostic factors for DFS and OS, respectively." (PMID 27391842, 2016). "Tumour expression of the biomarker amphiregulin (AREG) has also been correlated with survival during anti-EGFR therapy." (PMID 27764839, 2016). "A large number of information was available to support a role for AREG in tumor development and cancer cell biology." (PMID 25762634, 2015). "Most importantly, AREG was also identified to participate in the tumor resistance to PI3K inhibition and sorafenib therapy, and as the sole targeted agent in the treatment of advanced solid carcinomas." (PMID 25762634, 2015). "On day 28 after injection, the tumor size in the lung was significantly reduced when AREG expression was knocked down." (PMID 26503469, 2015). "Published microarray studies of early breast lesions, specifically hyperplastic enlarged lobular units, identified both AREG and EREG as genes that were significantly induced in these lesions." (PMID 26215578, 2015). "YAP, TAZ, and AREG are downstream effectors of the Hippo pathway and have been reported either as oncogene candidates or tumor suppressors." (PMID 24860833, 2014). "The AREG protein guarantees tumor cell self-sufficiency in generating growth signals, limitless replicative potential, and resistance to apoptosis." (PMID 25122487, 2014). "We also found that amphiregulin was a chemoattractant for mouse fibroblasts in migration and invasion assays, suggesting a mechanism of recruitment into the tumor, and that amphiregulin directly activated fibroblasts as judged by induction of α-SMA expression." (PMID 24068959, 2013). "Together, these results suggest that fibroblast-secreted amphiregulin has potent effects on tumor progression, with autocrine effects leading to activation of fibroblasts and paracrine effects protecting cancer cells from cell death." (PMID 24068959, 2013). "In our cohort, the survival of cetuximab-treated patients with KRAS wild type, AREG-low CRC (median 15 months) was as poor as the survival of patients with KRAS mutant tumours (17–22 months)." (PMID 23374602, 2013). "Compared to AREG, tumour EREG mRNA expession was a stronger predictor of cetuximab benefit in KRAS wild type cases in three more series." (PMID 23374602, 2013). "AREG mRNA reflects EGFR signalling in KRAS wild type tumours, predicting for cetuximab efficacy when high and failure when low." (PMID 23374602, 2013). "Although EGFR mRNA expression showed a relatively strong correlation between the primary tumor and metastases, the correlations of AREG and EREG, which are the ligands of the EGFR family, between primary and metastases were weaker than that." (PMID 22409860, 2012). "Culturing of A431 parental tumour cells with Ctx for 48 h remarkably diminished the expression of AREG/EREG proteins to very low or almost undetectable levels." (PMID 22491422, 2012).
tumor (continued). "We are beginning to accumulate evidence that AREG/EREG behave as universal markers for predicting the efficacy of Ctx across most types of EGFR-driven human tumours." (PMID 22491422, 2012). "Significantly, exosomal amphiregulin was found to be 5 times more efficient at increasing tumor invasiveness compared to the same concentration of soluble recombinant amphiregulin." (PMID 22738135, 2012). "Amphiregulin and epiregulin are ligands of EGFR and high gene expression is thought to reflect greater dependence of tumor growth on the EGF pathway and thus, greater susceptibility to EGFR inhibition." (PMID 24212785, 2011). "The expression of amphiregulin (AR) transcript was quantified in 10 tumour/normal pairs by qRT-PCR and correlated with expression of COX-2 in the same samples." (PMID 19558693, 2009). "Instead of producing IFN‐γ and TNF‐α, they elevate amphiregulin, a tumor‐promoting factor." (PMID 41082397, 2026). "Flow cytometry revealed that IFN‐γ is the predominant cytokine produced by NK cells upon IL‐12, IL‐15 and IL‐18 stimulation, and that AREG‐KO NK cell–CM induced more cell death than WT NK cell–CM, indicating that NK cell–derived AREG protects against IFN‐γ–mediated tumor cell apoptosis." (PMID 41082397, 2026). "Here, it dissects the molecular mechanisms underlying NK cell dysfunction in cutaneous malignancies and identifies a paradoxical cytokine shift in tumor‐associated NK cells–reduced production of IFN‐γ and TNF‐α alongside elevated amphiregulin (AREG), an EGFR ligand linked to tumor progression." (PMID 41082397, 2026). "Additionally, AREG depletion in iCAFs significantly suppressed their tumor‐promoting effects on tumor sphere and clone formation, while exogenous AREG administration markedly promoted tumor sphere and organoid formation." (PMID 39950944, 2025). "Furthermore, antibody-based therapies targeting AREG or targeting AREG shedding by ADAM17 antibody have demonstrated anti-tumor efficacy in preclinical models." (PMID 40725192, 2025). "The upregulation of EGFR and/or AREG upon entinostat treatment suggests that the tumor cells may become then more sensitive towards EGFR inhibition." (PMID 39864337, 2025). "A previous strategy was used because of the dual nature of Vδ1 T cells (Vδ1 T cells expressing high FITC anti‐human amphiregulin (AREG) levels promote tumor proliferation), which included secondary stimulation and induction with IL‐15/IL‐18 to achieve similar results." (PMID 40112194, 2025). "Further analysis revealed that YAP depletion and verteporfin treatment attenuated the transcription of TEAD target genes, such as AREG, CTGF, and CYR61, all of which are associated with diverse tumor-promoting activities, including enhanced metastatic potential and cancer cell proliferation." (PMID 40542295, 2025). "AREG also contributes to tumor progression by mediating the EMT process." (PMID 40593037, 2025). "Interestingly, we found through our NanoString analysis that exposure of HGSOC cells to AREG led to an upregulation in genes related tumor cell growth, angiogenesis, and immune evasion." (PMID 38831884, 2024). "The AREG/EGFR axis induces tumor cell proliferation through multiple signaling pathways." (PMID 38904011, 2024). "The conflicting roles of stromal-derived AREG in mediating mAb response may be due, in part, to varied tumor and stromal expression levels of AREG, with the latter potentially dependent on pretreatment with or without chemotherapy." (PMID 40727266, 2024). "AREG is overexpressed in various tumor types and is a poor prognostic marker." (PMID 39199549, 2024). "Using our extensive pan-cancer NK cell atlas, we were able to generate a solely NK cell-derived, tissue-residency signature (atlas-TR: PSMA2, SLC5A3, CCL4L2, CLN3, SCGB1A1, AREG), which outperformed the conventional literature-derived TR signature across tissue and tumor type." (PMID 38956379, 2024).